MVP (major vault protein)
Description:
Structural component of the vault particle, which is a massive ribonucleoprotein complex that may play a role in cargo transport and signal transduction. Oligomerizes to form a cage-like vault complex, which can house several minor vault components including PARP4. Vaults may play a role in nucleo-cytoplasmic transport. Down-regulates IFNG-mediated STAT1 signaling and subsequent activation of JAK. Down-regulates SRC activity and signaling through MAP kinases.
Synonyms: LRP; VAULT1
Tractability: Small molecule: a structure with a bound ligand is known. Antibody: its Gene Ontology location is reachable by antibodies, with high confidence. PROTAC: UniProt records ubiquitination sites on it; ubiquitination databases record sites on it; its protein half-life has been measured.
Gene: Protein-coding gene on chromosome 16 (29,820,394 to 29,848,039, forward strand). Ensembl gene ENSG00000013364.
Subcellular location: Cytoplasm; Nucleus, nuclear pore complex; Cytoplasm, perinuclear region
Subcellular location (Human Protein Atlas): Cytosol
Pathways (Reactome):
Immune System: Neutrophil degranulation
Gene Ontology:
Molecular function: identical protein binding; protein binding; protein kinase binding; protein phosphatase binding
Biological process: ERBB signaling pathway; intracellular signal transduction; negative regulation of epidermal growth factor receptor signaling pathway; protein transport; cell population proliferation; protein activation cascade
Cellular component: cytoplasm; cytoskeleton; cytosol; extracellular exosome; membrane; nucleus; perinuclear region of cytoplasm; extracellular region; ficolin-1-rich granule lumen; ribonucleoprotein complex; secretory granule lumen; nuclear pore
Genetic constraint (gnomAD): Loss-of-function variants: 62 observed, 81.45 expected, observed/expected ratio (o/e) 0.76, 90% interval 0.62 to 0.94. The upper end of that interval is the gene's LOEUF score, 0.94, which puts it in group 3 of 6, group 1 being the genes least tolerant of losing a copy. Missense variants: 1,000 observed, 1,218.7 expected, observed/expected ratio (o/e) 0.82, 90% interval 0.78 to 0.87. Synonymous variants: 505 observed, 513.24 expected, observed/expected ratio (o/e) 0.98, 90% interval 0.91 to 1.06.
Homologues: Orthologues: chimpanzee MVP (100% identical), macaque MVP (99% identical), dog MVP (91% identical), pig MVP (91% identical), rabbit MVP (90% identical), mouse Mvp (88% identical), rat Mvp (88% identical), guinea pig MVP (87% identical), tropical clawed frog mvp (69% identical), zebrafish mvp (66% identical).
Diseases named in the same sentence as MVP in open-access papers:
MVP is named in the same sentence as 96 diseases in open-access papers, as found by Europe PMC text mining. Sharing a sentence is not in itself a finding about the gene and the disease. The quoted sentences say what the papers report.
breast carcinoma (23 papers, 2005 to 2025). "In breast cancer cells, likewise, a high MVP level was associated with poor prognosis and the induction of chemotherapy resistant metastasis." (PMID 35681764, 2022). "Higher expression of VCP than MVP was verified in all healthy tissues representing secondary sites for breast cancer metastasis (breast, brain, bone, liver, lung, and lymph node)." (PMID 39802400, 2025). "In breast cancer, for instance, increased Notch1 upregulates MVP expression to activate the AKT pathway, which is involved in multidrug chemotherapy resistance and endothelial to mesenchymal transition promotion." (PMID 35681764, 2022). "Working on a cisplatin-resistant breast cancer cell line, Xiao and coworkers first observed that Notch1 knockdown resulted in MVP downregulation and concomitant AKT pathway suppression." (PMID 33572350, 2021). "In human breast cancer, MVP is upregulated in tumor cells at the invasive front, where they are in close contact to adipocytes, highlighting the clinical relevance of our results." (PMID 30654824, 2019). "In line with our recent findings, the results of a proteomic analysis revealed a role for BAG3 and Major Vault Protein as potent pro-survival factors that contribute to chemotherapy resistance in breast cancer cells." (PMID 26158518, 2015). "We observed a significant up-regulation of MRP-1 (p < 0.0001, Wilcoxon matched pairs test) and of MVP (p < 0.0023, Wilcoxon) in the breast cancer subgroup." (PMID 16026610, 2005). "A trafficking role has also been proposed for vaults in human cells based on the observations that MVP interacts with the estrogen receptor in MCF-7 breast cancer cells and with the tumor suppressor PTEN in HeLa cells." (PMID 15710043, 2005). "PTPN18 is translocated from the cytoplasm to the nucleus by MVP and importin β2 in breast cancer." (PMID 35982039, 2022). "Finally, adipocytes confer a multidrug resistance phenotype to breast cancer cells by increasing the nuclear efflux of Doxorubicin (DOX) through a major vault protein (MVP)-dependent process and its expulsion from breast cancer cells via EVs." (PMID 35646668, 2022). "It is known that induced MVP expression by adipocytes could contribute to an MVP-related multidrug-resistance phenotype in breast cancer cells." (PMID 35681764, 2022). "Nuclear import of PTPN18 inhibited breast cancer metastasis mediated by MVP and importin β2." (PMID 36556168, 2022). "Collectively, our study shows that adipocytes induce an MVP-related multidrug-resistant phenotype in breast cancer cells, which could contribute to obesity-related chemoresistance." (PMID 30654824, 2019). "In breast cancer cells, B7H3 promotes the population of cancer stem cells by binding to the major vault protein (MVP), which subsequently induces MEK through enhancing the interaction between B-RAF and MEK." (PMID 40214484, 2025). "In breast cancer, B7-H3 has been shown to activate the MEK signaling pathway through its interactions with major vault protein (MVP), leading to the proliferation of cancer stem cells in vitro." (PMID 40801642, 2025). "PTEN engages with the Major Vault Protein (MVP) through these NLS in PTEN’s C2 domain, ultimately leading to PTEN shuttling into the nucleus in breast cancer cells." (PMID 36830628, 2023). "Overall, these results support the idea that MVP and importin β2 cooperatively promote PTPN18 translocation from the cytoplasm to the nucleus in breast cancer cells." (PMID 35982039, 2022). "Consistent with our finding that the PY-NLS/importin β2 nuclear transport system regulates PTPN18 nuclear localization in the presence of MVP, we established that knockdown of importin β2 or MVP prevents PTPN18 nuclear accumulation in breast cancer." (PMID 35982039, 2022). "The depletion of either MVP or BAG3 inhibits the activation of ERK1/2, which in turn promotes adriamycin-induced apoptosis of breast cancer cells." (PMID 35681764, 2022).
breast carcinoma (continued). "It is also noteworthy that MVP upregulation by LDL and in breast cancer cells cocultivated with adipocytes, which suggests a link between lipid metabolic diseases and MVP-promoted cancer." (PMID 33572350, 2021). "Moreover, major vault protein (MVP) assists in discharging tumor-suppressive miRNA-193a from colon cancer cells via sEVs, hence promoting tumor progression, while AUF1-mediated recruitment of lncRNA-AFAP1-AS1 to breast cancer-derived sEVs is associated with trastuzumab resistance." (PMID 34496946, 2021). "The mechanisms of B7-H3 involved in cancer progression include binding to MVP, which regulates the activation of the MAPK kinase pathway and subsequently regulates breast cancer stem cell enrichment." (PMID 32602545, 2020). "In the series of patients where MVP expression was investigated by immunohistochemistry, we observed a slight but not significant enhancement of MVP expression at the tumor border (compared with the tumor center) in human breast cancers from overweight/obese as compared with lean patients." (PMID 30654824, 2019). "Therefore, our results suggested that 3oc enabled trastuzumab resistance for breast cancer cells, and this impact could not be attributed to the MVP–p38 axis in cell apoptosis, thus different from previous work with immune cells." (PMID 39786928, 2025).
colon carcinoma (22 papers, 2017 to 2025). "Other proteins have been implicated in RNA loading into exosomes, such as major vault protein (MVP) for miR-193a in colon carcinoma cell line, HuR for miR-122 in human hepatic cells, Arc protein for mRNA in neurons, etc.." (PMID 36674857, 2023). "We found heterozygosity for the LP MVP c.2296C>T p.Arg766X and IL32 c.515_516insG p.Asp172Glufs* variants in both the index case #11 and her mother, in whom colon cancer had been diagnosed at an early age." (PMID 40995433, 2025). "In colon cancer, elevated MVP expression not only promotes metastasis of colon cancer cells but also confers resistance to vinorelbine, revealing its multifaceted impacts on cancer progression." (PMID 39026679, 2024). "Major vault protein (MVP) can transport miR‐193a from colon cancer cells to exosomes and promote tumour progression." (PMID 36941028, 2023). "MVP overexpression in CT26 colon cancer cells leads to decreased abundance of miR-193a in the cells and increased levels in exosomes, suggesting the important role the MVP plays in the miR-193a transportation to exosomes." (PMID 36506304, 2022). "MVP knockout colon carcinoma cells led to an accumulation of cytosolic miR-193a and a decrease of miR-193a in cell-derived exosomes, while no change in miR-126a was observed." (PMID 34246289, 2021). "Several RBPs have been previously identified as mediators of exosome miRNA sorting in various model systems, including major vault protein in colon cancer cells, hnRNPA2B1 in T cells, and YBX1 in HEK293T cells." (PMID 32819370, 2020). "Yet, MVP also promotes survival and migration of glioblastoma, and suppresses apoptosis of human senescent diploid fibroblasts and human colon cancer cells." (PMID 31092229, 2019). "It has also been shown that MVP-mediated exosomal sorting of miR-193a promotes colon cancer progression." (PMID 31740664, 2019). "Induction of MVP in colon cancer tissue is stage-dependent and supported by confocal immunostaining and immunoblotting results." (PMID 28211508, 2017). "MVP KO in CT26 colon tumour cells resulted in the inhibition of liver metastasis of colon cancer, and this result correlates with an increase in miR-193a in CT26 cells and a decrease in miR-193a in exosomes." (PMID 28211508, 2017). "The MVP-mediated promotion of tumour progression through miR-193a is also demonstrated by subcutaneous injection of human colon cancer SW620 cells into nude mice." (PMID 28211508, 2017). "Interestingly, it was previously demonstrated that mouse colon cancer cells secrete exosomes containing MVP and that knockout of MVP led to miR-193a accumulation in donor cells instead of exosomes." (PMID 36980669, 2023). "In addition, major vault protein (MVP) mediates the sorting of exosomal miR-193a and promotes colon cancer progression." (PMID 34330299, 2021). "Also, MVP-mediated exosomal sorting of miR-193a promotes colon cancer progression through targeting of Caprin1, which upregulates Ccnd2 and c-Myc." (PMID 31402975, 2019). "MVP may facilitate metastasis of colon cancer due to its impact on cell migration." (PMID 34829999, 2021). "The authors delineated that, miR-193a interacted with major vault protein (MVP) in cells and was selectively packaged into exosomes leading to colon cancer metastasis to the liver." (PMID 33805398, 2021). "MVP has been reported to activate the EGFR/PI3K/AKT signaling pathway in glioblastoma and colon cancer cells." (PMID 31092229, 2019).
glioblastoma (11 papers, 2007 to 2025). The most malignant astrocytic tumor (WHO grade IV). "In this study, the expression of MVP by siRNA was reduced causing the impairment of migratory and invasive competencies and decreasing the resistance of glioblastoma cells to starvation in vitro and in vivo." (PMID 34829999, 2021). "In glioblastoma, MVP expression was shown to be significantly increased and appears to be related to the malignancy of the tumor and to the survival rate of cancer patients." (PMID 35681764, 2022). "Current data indicate the participation of MVP not only in multidrug resistance, but also in the aggressiveness of the tumor cells, as presented for the glioblastoma multiforme model." (PMID 34829999, 2021). "A second distinct consequence of MVP overexpression was uncovered by culturing glioblastoma cells under serum-starved conditions." (PMID 24243798, 2013). "In a previous study, we observed correlation between MVP expression of glioblastoma cells and resistance to anthracyclines, which suggests a contribution of MVP at least to doxorubicin hypersensitivity of BTL3 cells." (PMID 17342095, 2007). "Thus, MVP represents an interesting target for novel treatment approaches for brain cancer, including glioblastoma." (PMID 35681764, 2022). "Consequently, overexpression of MVP resulted in a higher invasion rate of human glioblastoma xenograft models." (PMID 34829999, 2021). "Consequently, MVP overexpression resulted in enhanced growth and brain invasion in human glioblastoma xenograft models." (PMID 24243798, 2013). "In temozolomide-resistant glioblastoma U251 and LN229 cells, MVP was found upregulated, and when it was silenced, the sensitivity to temozolomide was increased and the sphere formation ability and invasive capacity of the cells were reduced." (PMID 40004027, 2025). "It was shown that in human glioblastoma (GBM) cells, MVP is upregulated (albeit by unknown mechanisms), which is paralleled by activation of migratory and invasive potential." (PMID 33572350, 2021). "Thus we address the questions whether MVP itself has a pro-tumorigenic function in glioblastoma." (PMID 24243798, 2013). "Given that nuclear PTEN induces G1 cell cycle arrest, while cytoplasmic PTEN promotes apoptosis, MVP’s regulation of PTEN’s nuclear–cytoplasmic distribution may play a pivotal role in its anti-apoptotic and tumor-promoting effects observed in glioblastoma." (PMID 40004027, 2025). "In addition, MVP overexpression results in enhanced growth and brain invasion through the EGFR/PI3K signaling pathway in human glioblastoma xenograft models." (PMID 35681764, 2022).
hepatocellular carcinoma (11 papers, 2013 to 2025). A malignant tumor that arises from hepatocytes. "In a more recent report, it was also determined that forced MVP expression was sufficient to trigger hepatocellular carcinoma (HCC) in mice, which highlights a possible causal relationship between HBV or HCV infections and the onset of the cancer disease." (PMID 33572350, 2021). "A recent study has provided compelling evidence for the role of MVP in hepatocellular carcinoma (HCC)." (PMID 39026679, 2024). "FGF21 promotes ferroptosis in hepatocellular carcinoma by upregulating Major vault protein (MVP), which enhances NOX4-mediated ROS production through IRF1 and YAP1 interactions." (PMID 39315094, 2024). "Moreover, the infections of hepatitis B virus and hepatitis C virus, which are known to increase the risk of hepatocellular carcinoma (HCC), elevate MVP expression." (PMID 35681764, 2022). "Of note, resistance of human hepatoma cells was also associated with major vault protein (MVP) expression, a protein also known as lung-resistance related protein that is widely distributed in normal tissue and overexpressed in multidrug-resistant cancer cells." (PMID 26729094, 2015). "Interestingly, this seems to be a lineage-specific effect since in the case of hepatoma cell lines we observed gefitinib resistance as a consequence of MVP overexpression." (PMID 24243798, 2013). "It has been shown that MVP can also be expressed on the surface of a variety of cell lines, including hepatocellular carcinoma (HCC) cells." (PMID 40004027, 2025). "Likewise, elevated MVP expressions in HBV-infected patients and hepatoma cell lines were also detected and a specific viral protein (HBx) was shown to stimulate MVP promoter activity." (PMID 33572350, 2021).